MYD88 (MYD88 innate immune signal transduction adaptor)
Diseases named in the same sentence as MYD88 in open-access papers (continued):
Sharing a sentence is not in itself a finding about the gene and the disease.
gastric cancer (16 papers, 2015 to 2025). A primary or metastatic malignant neoplasm involving the stomach. "A study utilizing MyD88 deficient (MyD88−/−) mice found that mice challenged with H. felis developed significant severe lesions that rapidly progressed to gastric cancer in situ compared to wild-type mice." (PMID 35683528, 2022). "In conclusion, we identified a functionally relevant homozygous missense variant in MYD88 and a defective Th17 response in a patient with recurrent infections and early-onset gastric cancer." (PMID 26700889, 2016). "MyD88 is an essential adaptor protein for most Toll-like receptors and IL-1 family receptors, and its genetic variants are associated with increased gastric cancer risk in humans, particularly in the context of Hp infection where bacterial recognition and inflammatory responses are critical." (PMID 40673273, 2025). "Our data suggest that a genetic defect in MYD88 results in an impaired immune response and may increase gastric cancer risk." (PMID 26700889, 2016). "Additionally, a genetic defect in MyD88 has been identified in gastric cancer and may increase the risk of developing this type of cancer." (PMID 38129809, 2023). "Using whole-exome sequencing, we identified a novel germline homozygous MYD88 variant, which probably explains the patient’s vulnerability to C. albicans and other infections that might have contributed to the development of her gastric cancer." (PMID 26700889, 2016). "Intriguingly, MyD88 depletion significantly weakened the promotive effect of GRB7 overexpression on malignant phenotypes of gastric cancer cells." (PMID 38129809, 2023). "The TCGA data revealed that MyD88 expression was positively correlated with the GRB7 expression in gastric cancer tumor samples." (PMID 38129809, 2023). "Our in vitro functional assays further revealed that MyD88 partially reversed the promotion of cell proliferation and migration caused by GRB7 overexpression in gastric cancer." (PMID 38129809, 2023). "Silencing MyD88 was observed to alleviate the malignant phenotypes promoted by GRB7 in gastric cancer cells." (PMID 38129809, 2023). "In a similar study on the role of the gastric microbiome in gastric cancer development, the microbiome composition from MyD88−/− mice was compared to that of wild-type, Trif Lps2, and double knockout (DKO) mice." (PMID 35683528, 2022). "Myeloid differentiation primary response gene 88 (MyD88) regulates helicobacter-induced gastric cancer progression." (PMID 35683528, 2022). "This study was designed to identify MyD88-dependent genes involved in the progression towards gastric cancer during the course of Helicobacter infection." (PMID 28201999, 2017). "Another highly downregulated gene we found in Myd88−/− mice infected with H. felis was Apoa1, which was also reported to be downregulated in a fast progressing gastric cancer mouse model." (PMID 28201999, 2017). "In this study, we have identified genes that are involved in the rapid progression of Helicobacter-induced gastric cancer that are also potentially regulated by MyD88." (PMID 28201999, 2017). "We have previously shown that a key signal transduction adaptor protein, myeloid differentiation primary response gene 88 (MyD88), regulates Helicobacter-induced gastric cancer progression in a mouse model of gastric cancer." (PMID 28201999, 2017). "Furthermore, it was discovered that GRB7 regulated malignant cellular characteristics through MyD88 in gastric cancer." (PMID 38129809, 2023). "Therein, we speculated that GRB7 may affect MyD88 expression to regulate gastric cancer progression." (PMID 38129809, 2023). "Notably, MyD88 is an intracellular adaptor protein that highly expressed in gastric cancer, and played a critical role in gastric cancer progression, we thus focused on the MyD88 in the following analysis." (PMID 38129809, 2023). "Previous studies on intestinal tumors and gastric cancer showed that TLR/MyD88 signaling could regulate its downstream COX-2/PGE2 axis." (PMID 37153547, 2023).
gastric cancer (continued). "This is in agreement with our findings that show a potential connection between gastric cancer and Lactobacillus, and further indicates that the Myd88−/− model of fast-progressing gastric cancer recapitulates a gastric microbiome change noted in human populations." (PMID 33477306, 2021). "However, in Myd88−/−, our fast-progressing gastric cancer model, we observed a reduction in Campylobacterales abundance at 3 months and 6 months." (PMID 33477306, 2021). "No additional germline mutations in MYD88 were found in our cohort of 126 patients suspected of hereditary gastric cancer." (PMID 26700889, 2016). "Together, these results suggest MyD88 may contribute to GRB7-mediated gastric cancer progression." (PMID 38129809, 2023). "A sharp increase in Lactobacillales in infected Myd88−/− and DKO mice at 3 and 6 months was observed as compared to TrifLps2 and WT mice, hinting at a possible role of these bacteria in gastric cancer progression." (PMID 33477306, 2021). "The interplay between TLR/MyD88 and COX-2/PGE2 pathways also contributes to inflammatory response of gastric cancer." (PMID 33144870, 2020). "In gastric cancer, it has been shown that the TLR/MyD88 pathway is needed for the inflammatory response in tumor tissues, and plays a role in maintenance of stemness in gastric tumor cells." (PMID 28637493, 2017). "Next-generation sequencing of unexplained young or familial gastric cancer cases without CDH1 mutations revealed that CTNNA1, MYD88, and MAP3K6 had deleterious mutations associated with gastric cancer." (PMID 36741258, 2023). "Comparison of the gastric microbiome from Myd88−/− mice to WT, TrifLps2 and DKO mice, we were able to intensively analyze how changes in Lactobacillales could be connected to gastric cancer development and progression." (PMID 33477306, 2021).
heart failure (16 papers, 2013 to 2026). Inability of the heart to pump blood at an adequate rate to meet tissue metabolic requirements. "The critical role of MyD88 signaling in preserving cardiac function and limiting progression to heart failure was also shown in a dominant negative MyD88 transgenic mouse model." (PMID 39271818, 2024). "A similar behavior was seen for MyD88 myddosome, another macromolecular complex involved in heart failure and cardiac fibrosis after exposure to viral and chemical agents with cardiotoxic properties." (PMID 34178667, 2021). "Consistent with the cardiacdysfunction phenotype, mRNA levels of ANF and BNPwere elevated in MyD88 TG myocardium by 2 and 5 months of age compared with WT mice,which indicated that the molecular program for heart failure had been initiated." (PMID 26628395, 2016). "Additionally, upregulation of the lncRNA cardiac hypertrophy-related factor (CHRF) in cardiomyocytes can upregulate myeloid differentiation primary response 88 (MYD88), inducing cardiomyocyte hypertrophy and apoptosis, leading to heart failure." (PMID 38585701, 2024). "Cardiac Hypertrophy-Related Factor (CHRF) is upregulated in both hypertrophic mouse hearts and human biopsies of patients with heart failure and functions as a sponge for miR-489, regulating Myeloid differentiation primary response gene 88 (Myd88) as downstream target of miR-489." (PMID 39086960, 2022). "Interestingly, ourprevious studies using cardiac-specific dominant negative MyD88 (dnMyD88) transgenicmice demonstrated that uncontrolled MyD88 signaling triggers dilated cardiomyopathy andspontaneous heart failure." (PMID 26628395, 2016). "Heart failure is closely associated with re-expression of fetal genes or upregulationof cardiac proteins, such as ANF and BNP.To more rigorously characterize the phenotype of MyD88 transgenic mice, mRNAexpression of heart failure markers was performed." (PMID 26628395, 2016). "We previously demonstrated that TLR4 expression levels and activity (Myd88 as a marker) are increased in brainstem of MI-induced heart failure, and that blockade of brain angiotensin II type 1 receptor decreased brain TLR4 with the attenuation of LV remodeling and sympathoexcitaion." (PMID 23874864, 2013). "As a positive regulator, IL1 upregulates MAPK and NFkB signaling pathways via myeloid differentiation factor-88 (MyD88), and both IL1R-/- and MyD88-/- mice display reduced fibrosis and progression toward heart failure in a model of acute myocarditis." (PMID 35138248, 2022). "Our data suggested thatoverexpression of MyD88 did not trigger obvious abnormality in heart morphology, butpromoted mild cardiac dysfunction at baseline, with an elevation in heart failure markerexpression." (PMID 26628395, 2016).
inflammatory bowel disease (16 papers, 2014 to 2025). A spectrum of small and large bowel inflammatory diseases of unknown etiology. "MyD88 expressed by B cells has been shown to inhibit DSS-induced exacerbation of inflammatory bowel disease by secreting IgA and IgM in response to damaging intestinal microbiota dissemination." (PMID 35909691, 2022). "A recent report showed a new soluble protein from LGG, HM0539, suppress inflammation by inhibiting the TLR4/MyD88/NF-κB signaling, which is considered as a potential therapeutic option for inflammatory bowel disease (IBD)." (PMID 36569920, 2022). "Here we show that CD4+Foxp3+Tregs produce the effector cytokine IL-17A during oropharyngeal candidiasis (OPC) and inflammatory bowel disease in a TLR-2/Myd88 signaling dependent manner." (PMID 25790134, 2015). "Several researches have showed that various TCM formulations and compounds could alleviate inflammatory bowel diseases through TLR4/MyD88 pathway, nonetheless whether modified PD takes effect through via this signaling still needs further investigation." (PMID 32517784, 2020). "However, the role of MyD88 in the pathogenesis of inflammatory bowel disease is controversial." (PMID 38946731, 2024). "MYD88 has been shown to be important for regulation of CD4+ T cells, including in promoting activation in the murine inflammatory bowel disease model." (PMID 32119719, 2020). "Research has confirmed that pro-inflammatory cytokines such as IL-1β, TNF-α, IL-18, along withsignaling molecules like MyD88 and NF-κB, play central roles in regulating inflammatory responses and have been established as core biomarkers in DSS-induced inflammatory bowel disease (IBD) models." (PMID 41227621, 2025).
rheumatoid arthritis (16 papers, 2012 to 2025). A chronic, systemic autoimmune disorder characterized by inflammation in the synovial membranes and articular surfaces. "TLR7 is widely distributed in immune cells, which can bind to MyD88 to initiate downstream inflammatory cascade responses, and is involved in rheumatoid arthritis progression." (PMID 38543188, 2024). "Dimerization of the myeloid differentiation primary response 88 protein (MyD88) plays a pivotal role in the exacerbated response to innate immunity-dependent signaling in rheumatoid arthritis (RA)." (PMID 37749630, 2023). "Indeed, the genes downregulated by MyD88 inhibition were consistent with the IPA-predicted disease associations directly related to RA, such as systemic autoimmune syndrome, rheumatic disease, inflammation of joint, and rheumatoid arthritis." (PMID 35002734, 2021). "TLRs also promote the inflammatory and destructive processes in rheumatoid arthritis with adapters MyD88 and MAL/TIRAP having a significant role." (PMID 23305364, 2012). "Moreover, the findings indicated that baicalin has the potential to reduce joint inflammation and tissue damage in a rat model of collagen-induced arthritis (CIA) by modulating the TLR2/MYD88/NF-κB p65 signaling pathway, thus offering a novel therapeutic approach for rheumatoid arthritis management." (PMID 40510367, 2025). "MYD88 has been found to be involved in IBD pathology and the involvement of MYD88 in response to TNF-blocking drugs has been demonstrated in studies on rheumatoid arthritis (RA) patients." (PMID 25015298, 2014). "The involvement of the TLR signaling in rheumatoid arthritis (RA) was shown on mice lacking MyD88 or TLR2 that were resistant to the induction of the disease." (PMID 23305364, 2012).
acute kidney injury (14 papers, 2011 to 2025). Sudden and sustained deterioration of the kidney function characterized by decreased glomerular filtration rate, increased serum creatinine or oliguria. "The activation of innate immunity via myeloid differentiation factor 88 (MyD88) contributes to ischemia reperfusion (I/R) induced acute kidney injury (AKI) and chronic kidney injury." (PMID 27246399, 2016). "Several studies document a similar role for TLR2, TLR4, and MyD88 in postischemic acute renal failure of C57BL/6 mice." (PMID 21544241, 2011). "However, further study incorporating the use of gene knock-out mice for TLR4, MyD88 and/or NF-κB should be performed in order to confirm the role of TLR4/MyD88/NF-κB pathway activation in dexmedetomidine mediated attenuation of acute kidney injury after orthotopic autologous liver transplantation." (PMID 26585410, 2015). "Myeloid differentiation factor 88 (MyD88), a central adaptor in the TLR4 pathway and a known contributor to acute kidney injury, showed increased protein expression in kidneys from septic rats, as determined through Western blotting and confirmed through immunohistochemistry/immunofluorescence." (PMID 40869248, 2025). "In addition to HMGB1, histones released from damaged renal cells in acute kidney injury (AKI) triggered neutrophil recruitment and renal inflammation via interaction with TLR2 and TLR4, in turn activating MyD88, NF-κB and mitogen activated protein kinase (MAPK) signaling." (PMID 32731558, 2020).
endotoxemia (14 papers, 2012 to 2025). "To further understand the mechanisms underlying the enhanced protection of Ber against endotoxemia by Y, we investigated the effects of Ber and Y on MyD88-dependent and independent pathways as well as cytokine production in LPS-treated mouse peritoneal macrophages." (PMID 23285207, 2012). "Ameliorated microbiota dysbiosis, increased the production of short-chain fatty acids, and alleviated endotoxemia by inhibiting the TLR4/MyD88/NF-κB signaling pathway." (PMID 37485384, 2023). "The relative contribution of MyD88-dependent signaling in CNS inflammation could be further elucidated by comparing neuroinflammatory responses in CLP and endotoxemia model in constitutive MyD88 null mutant mice." (PMID 26790027, 2016). "It was found that dexmedetomidine at the doses of 10 and 20 μg/kg decreased CLP-induced pulmonary inflammation and mortality, reduced production of IL-6 and TNF-α in plasma and BALF of septic rats, and suppressed TLR4/MyD88 expression and NF-κB activation in lung of endotoxemia rats induced by CLP." (PMID 23690665, 2013). "In contrast, dietary patterns characterized by high saturated fat and refined carbohydrate intake—negatively weighted within the DI-GM—have been associated with gut dysbiosis and elevated endotoxemia, which may exacerbate periodontal inflammation via TLR4/MyD88 pathways." (PMID 40880748, 2025). "In endotoxemia, PHLDA1 inhibits pro-inflammatory responses by repressing the TLR4/MyD88/NF-κB pathway through TOLLIP." (PMID 39735680, 2025). "It improved AOM/DSS-induced microbial dysbiosis, increased the production of short-chain fatty acids, alleviated endotoxemia, and improved intestinal shielding function by inhibiting TLR4/MyD88/NF-κB signaling." (PMID 40507156, 2025). "Alleviation of endotoxemia was further supported by the decreased expression of TLR4 and its downstream signaling protein Myd88 in the liver after FMT intervention." (PMID 28484247, 2017).
epilepsy (14 papers, 2015 to 2026). A brain disorder characterized by episodes of abnormally increased neuronal discharge resulting in transient episodes of sensory or motor neurological dysfunction, or psychic dysfunction. "Bringing this approach into the context of specific targets in epilepsy, it is possible to track the downstream effects of MyD88 and NOX2 loss-of-function in cell-type-specific." (PMID 35859905, 2022). "Furthermore, the mRNA levels of Irf3, Tlr4, Myd88, and Irak4 genes—encoding innate immune system markers essential for maintaining neuronal excitation/inhibition balance and implicated in epilepsy—were examined." (PMID 40608247, 2025). "Recent studies have documented MyD88 upregulation in epilepsy models, and inhibition of MyD88 significantly suppressed seizure and neuronal apoptosis in animal models." (PMID 30112701, 2018). "Studies have shown that MyD88 inhibition reduces damage and neuronal apoptosis in epilepsy." (PMID 40452925, 2025). "Several researches showed that TLR4 could mediate autophagy, and suppressed the apoptosis and autophagy by inhibition of the TLR4/MyD88 pathway in hippocampal neurons of epilepsy mice model." (PMID 32108135, 2020). "Our data suggest that MyD88 may represent a potential target for epilepsy treatment owing to its ability to affect MG/MΦ polarization." (PMID 30112701, 2018). "Moreover, the TLR4/MYD88/NF-κB/NLRP3 inflammasome pathway may be an important target for epilepsy treatment." (PMID 34421582, 2021). "In epilepsy, TLR4 signaling triggers glial activation and cytokine release via the MyD88–NF-κB pathway, enhancing neuronal excitability and BBB permeability." (PMID 41007696, 2025). "Within the network, many genes are related to inflammation and apoptosis, such as MAPK1, ATM, MYD88, RBL1, TRAF6, PIK3CD, IFNAR2, etc, indicating that these miRNAs may play a role in drug-resistant epilepsy through inflammation and apoptosis." (PMID 25984652, 2015).